CCL4 (C-C motif chemokine ligand 4)
Diseases named in the same sentence as CCL4 in open-access papers (continued):
Sharing a sentence is not in itself a finding about the gene and the disease.
Alzheimer disease (13 papers, 2012 to 2024). A progressive, neurodegenerative disease characterized by loss of function and death of nerve cells in several areas of the brain leading to loss of cognitive function such as memory and language. "This network contains the proinflammatory cytokine Il1a, previously associated with Alzheimer’s disease, development and plasticity, immune associated genes (Cd80, Cr2, Cd27, Dapp1) and chemokines (Ccl3, Ccl4, Ccl21)." (PMID 23742273, 2013). "Elevated CCL4 levels may be associated with Parkinson’s disease, Alzheimer’s disease, and blood–brain barrier dysfunction (neurodegenerative diseases are statistically more common in Yakutia)." (PMID 39769502, 2024). "Using proximity extension assay, two inflammatory cytokines (MCP-1 and CCL4) were increased, and one (PD-L1) was reduced in patients with iNPH compared with Alzheimer’s disease, mild cognitive impairment, and frontotemporal dementia." (PMID 37833765, 2023). "We also observed weak evidence of a causal effect of 1 SD increase in concentrations of MIP-1b (CCL4) (IVW: OR = 1.04 95% CI: 0.99 to 1.09, p = 0.08) and Eotaxin (IVW: OR = 1.08 95% CI: 0.99 to 1.17, p = 0.10) on risk of Alzheimer’s disease." (PMID 35580794, 2022). "We observed some evidence for a detrimental effect of greater levels of CTACK (CCL27), MIP-1b (CCL4), Eotaxin, GROa (CXCL1), MIG (CXCL9), IL-8 and IL-2 on the risk of Alzheimer’s disease." (PMID 35580794, 2022). "Based on former reports, CCL2 and CCL4 were thought to promote inflammation in the models of Alzheimer’s disease, while IL23 inhibits inflammation." (PMID 29959371, 2018). "CCL4 is secreted from glial and astrocytes, and involved in the progression of various brain diseases, including Alzheimer’s disease, multiple sclerosis, and ischemic brain disease, though its function in the brain remains unclear." (PMID 34199615, 2021). "MIP-1b (CCL4), IL-8 (CXCL8), and MCP-1 (CCL2) have all been identified as pro-inflammatory chemokines and can induce the migration of leukocytes to a desired site and have also been implicated in other inflammatory diseases such as multiple sclerosis, Alzheimer's disease, and HIV." (PMID 22359672, 2012). "CTACK (CCL4), MIG (CXCL9), GROa (CXCL1), MIP-1b (CCL4), Eotaxin (CCL11) and IL-8 belong to the chemokine family and evidence suggest that they could potentially play a role in Alzheimer’s disease." (PMID 35580794, 2022). "As CCL3 and CCL4 are key proinflammatory chemokines and inflammation is key in the progression of human diseases, the link between IDE and chronic diseases such as Alzheimer’s disease may be in part due to the role of IDE in controlling the inflammation." (PMID 25636406, 2015).
lung cancer (13 papers, 2018 to 2025). A malignant neoplasm involving the lung. "Another study reported that T/A/A CCL4 haplotype increased the risk of lung cancer in a Chinese population." (PMID 35463731, 2022). "Such cytokines upregulate CD8+ T cell production of CCL3 and CCL4, which alter Treg trafficking and ultimately contribute to the accelerated growth of lung cancer." (PMID 40553564, 2025). "The over-expression of CCL4 in oral squamous cell carcinoma and lung cancer increased lymphangiogenesis and vascular endothelial growth factor c expression and PD-L1." (PMID 38067251, 2023). "Studies have reported that several chemokines, such as CCL2, CCL5, CCL4, CXCL19, and CXCL12, are associated with the progression, metastasis, and prognosis of lung cancer." (PMID 36118890, 2022). "Marked changes in gene expression were measured for Ccl2, Ccl7, Ccl17, Ccl22, Ccl3, Ccl4, Il-1α, Il-1ß, and Il-1rn (inflammation), Lpo and Noxo1 (oxidative stress), and Mmp12 (inflammation/lung cancer)." (PMID 29463257, 2018). "Furthermore, IFN-γ neutralization alone resulted in an overall reduction of CCL3 and CCL4 produced by CD8+ T cells in the lung cancer tumor bed." (PMID 40553564, 2025). "Importantly, the ability of Spi-B, a lymphocyte lineage-specific Ets transcription factor, to promote the invasion of macrophages in human lung cancer is inhibited when the CCL4 gene is deleted." (PMID 35884919, 2022). "The Macro-1 cluster was transcriptionally similar to tissue-resident macrophages as reported in primary ccRCC, breast and lung cancers, and expressed markers such as SEPP1, FOLR2, CCL3, CCL4, and CXCL12." (PMID 38281962, 2024). "We found that CCL3, CCL4, and CSF1 were significantly upregulated in IL17D–expressing human lung cancer cells, whereas Ccl3, Ccl4, and Il6 were induced in IL17D–expressing murine lung cancer cells." (PMID 35939336, 2022). "The mRNA expression of CCL3, CCL4, and CSF1 was significantly upregulated in IL17D–expressing A549 cells compared with that in control cells, whereas IL17D overexpression in the murine lung cancer cell line LLC1 increased Ccl3, Ccl4, and Il6 expression." (PMID 35939336, 2022). "In summary, the current study demonstrates that Spi-B-positive lung cancer cells play an important role in increasing TAM recruitment by upregulating the expression of various cytokines, such as CSF2, IL6, CCL3, and CCL4." (PMID 34141615, 2021). "Furthermore, high levels of IFN-γ in both murine and human lung cancers, some produced by lung cancer cells themselves, contribute to accelerated tumor growth through promoting the production of CCL3 and CCL4 by CD8+ T cells." (PMID 40553564, 2025).
malaria (13 papers, 2013 to 2025). Malaria is a serious and sometimes fatal disease caused by a parasite that commonly infects a certain type of mosquito which feeds on humans. "We observed increased IL-4, CXCL1, CXCL2, and CCL4 within the placenta, which have all been reported to be increased in humans, mice, or in vitro models of malaria (49, –, 52)." (PMID 40470930, 2025). "However, for the malaria group, four distinct correlation patterns were observed; first pattern (CCL4, CCL2, CCL3, IL12 and IL2), second pattern (IL-17A, IL-1β, CCL11, IL4), third pattern (IL5, IL7, IL13), and fourth pattern (IL1RA, CXCL10, TNFα, IL2R, CXCL9, IL6)." (PMID 35811678, 2022). "Gabonese children with severe malaria were found to have elevated levels of CCL3 and CCL4 in their circulation." (PMID 32373101, 2020). "Additional cytokines were elevated in malaria cases compared to healthy controls and included IL-1ra, IL-10, IL-8/CXCL8, and macrophage inflammatory protein 1β (MIP-1β)/CCL4." (PMID 28775960, 2017). "In another study, IL-8/CXCL8 was elevated in CSF of non-fatal CM cases of P. falciparum-infected children, while MCP-1/CCL2, MIP-1α/CCL3, MIP-1β/CCL4, and RANTES/CCL5 levels were comparable to malaria-free controls." (PMID 28775960, 2017). "Plasma levels of inflammatory cytokines (IFNα, IFNγ, TNF, IL-6) and chemokines (CCL2, CCL3, CCL4, CXCL10) were significantly higher during severe malaria compared to convalescence." (PMID 27792766, 2016). "Amongst the clinical groups evaluated, the group of individuals with malaria and dengue co-infection exhibited the highest median concentrations of IFN-γ, IL-6, CCL4." (PMID 26271921, 2015). "The expression levels of CXCL10 (5.3-fold) was highest during the early phase of malaria, while CCR3 and CCL4 were higher during febrile and recovery stages of the disease." (PMID 24188121, 2013). "In severe malaria in Malawian children, the inflammatory monocyte subset was expanded and activated with higher plasma levels of inflammatory cytokines (IFNα, IFNγ, TNF-α, IL-6) and chemokines (CCL2, CCL3, CCL4, CXCL10) than in convalescence." (PMID 30581439, 2018). "In addition, in vitro differentiated syncytiotrophoblasts have been shown to produce CCL3, CCL4 and CXCL8 in response to stimulation with malaria hemozoin, which is highly abundant in the placenta during PM." (PMID 24476686, 2014). "Moreover, cerebrospinal fluid levels of CXCL10, CXCL8 and CCL4 have been found to be significantly higher in children with CM compared with children with SMA and non-malaria-infected individuals." (PMID 24476686, 2014). "We report high plasma levels of proinflammatory cytokines and chemokines (IFNγ, TNF, IL-6, CCL2, CCL3, CCL4, CXCL10) in severe malaria patients compared to baseline uninfected follow-up, which matched that of Py infection in mice in which we could conduct a temporal analysis." (PMID 27792766, 2016).
multiple sclerosis (13 papers, 2012 to 2025). A progressive autoimmune disorder affecting the central nervous system resulting in demyelination. "For example, MIP1B/CCL4 is linked to multiple sclerosis, post-traumatic stress disorder, and depression." (PMID 39574895, 2024). "Through an intensive literature search in PubMed, we selected CCL4 as the central hub gene because of its known pathogenic role in autoimmune diseases including rheumatoid arthritis (RA), multiple sclerosis (MS) and Behcet’s disease." (PMID 34975900, 2021). "CCL4 is a biomarker of multiple sclerosis and associated with inflammation and T-cell activation." (PMID 34025649, 2021). "CCL4 is upregulated in several neurological disorders such as multiple sclerosis, Parkinson’s disease, and AD." (PMID 37833765, 2023). "CCL4 is related to the pathogenesis of several diseases, including sarcoidosis, cystic fibrosis, and multiple sclerosis." (PMID 36978012, 2023). "CCL4 is secreted from glial cells and astrocytes in the CNS and has been suggested to be involved in the progression of various brain diseases, including AD, multiple sclerosis, and ischemic brain disease." (PMID 38622654, 2024). "Ccl4 is a proinflammatory chemokine that is known as a chemo-attractant for monocytes and T cells and has been suggested to play a part in various nervous system pathologies such as inflammation, trauma, ischemia and multiple sclerosis (Semple, Kossmann & Morganti-Kossmann, 2010)." (PMID 24282673, 2013).
rheumatoid arthritis (13 papers, 2017 to 2026). A chronic, systemic autoimmune disorder characterized by inflammation in the synovial membranes and articular surfaces. "In autoimmune diseases, studies have found a correlation between CCL4 polymorphisms and the risk of rheumatoid arthritis (RA)." (PMID 37287987, 2023). "We want to investigate whether the single nucleotide polymorphisms (SNPs) of the CCL4 gene can predict the risk of rheumatoid arthritis (RA)." (PMID 29955612, 2018). "Studies showed that various chemokines participated in RJD pathogenesis: rheumatoid arthritis patients exhibit increased levels of plasma CCL2, CCL3, CCL4, and CXCL10 and psoriatic arthritis patients also exhibited high values of CCL2 and CXCL10." (PMID 38622714, 2024). "In the clinical setting, a high degree of concordance has been demonstrated between the status of oxidative stress in rheumatoid arthritis and the levels of MIP-1β/CCL4 and MCP-1/CCL-2." (PMID 36293292, 2022). "In the bootstrap resampling, we selected several important rheumatoid arthritis genes such as MMP genes (MMP1, MMP3), CCL genes (CCL3, CCL4, and CCL26), and IL genes (IL6, IL8, IL19, and IL24)." (PMID 31371761, 2019). "Recently, increased miR-155 is shown to be associated with increased production of the chemokines CCL3, CCL4, CCL5 and CCL8, and regulate chemokine receptor expression in rheumatoid arthritis patients." (PMID 29162878, 2017). "In four cases, our top SNV had been associated with an inflammatory disease in previous GWAS: rs113010081/CCL4 with inflammatory bowel disease, rs1569723/CD40 with Crohn’s disease, rs4239702/CD40 with rheumatoid arthritis and rs11230563/CD6 with ulcerative colitis." (PMID 31727947, 2019).
co-infection (12 papers, 2011 to 2025). "In addition, the qPCR analysis showed the chemokines ccl4, ccr6, ccr9, and cd5 were significantly down-regulated during lice infection alone vs pre-infection, and comparable with that of co-infection." (PMID 35046944, 2021). "Coinfection led to prolonged viral persistence, enhanced pulmonary immune cell infiltration, and significantly elevated levels of inflammatory cytokines (IL-6, CCL3, CCL4, and G-CSF; p < 0.05–0.001), culminating in severe pneumonia." (PMID 41226526, 2025). "Additionally, co-infection of pigs with NADC30-like PRRSV-2 strain SDlz1601 and S. suis upregulated IL-1β, IL-6, IL-8, TNF-α, CCL4, IL-10, and INF-β in PAMs." (PMID 38547254, 2024). "Co-infection of monocytes with PRRSV-2 strain IAF-Klop and S. suis led to synergistic effects on the expressions of IL-6, CCL5, and TNF-α, and additive effects on productions of CCL4, CCL14, CCL20, IL-15, and PTGS2 (COX-2)." (PMID 38547254, 2024). "However, it has been reported that both infections involve different proinflammatory cascades such as CCL4 and AhR, which can perpetuate and exacerbate the clinical presentation of SARS-CoV-2 and DENV co-infection." (PMID 37580025, 2023). "In addition, CCL4, CXCL1, and CXCL2 expression in the co-infection group was highly significant, while CX3CL1 and XCL1 expression was equivalent to that in mock control." (PMID 33968006, 2021).
liver inflammation (12 papers, 2020 to 2025). "Taken together, these findings indicate that sja-let-7 attenuated progression of CCL4-induced LF and ameliorated liver inflammation in vivo." (PMID 38132291, 2023). "On the other hand, the dose of 5 or 10 mg/kg of Mel-PLGA NPs showed a marked ameliorating effect on CCL4-induced liver inflammation." (PMID 37777583, 2023). "The accumulation of γδ T cells in the liver in CCL4-induced hepatitis has been reported to be CCR6-dependent." (PMID 37475963, 2023). "In the current study, the effect of DSL-EA extract in CCL4-induced liver inflammation was assessed through a series of hematological, biochemical, enzymatic, and histological studies." (PMID 35342748, 2022). "Elevated blood levels of proinflammatory cytokine MIP1B, also known as CCL4, are observed in liver inflammation and fibrosis." (PMID 34635168, 2021). "Likewise, the results of the DTR-Foxp3 CCL4-induced liver damage model indicate that the small size of the intra-hepatic Treg pool exerts limited immunoregulatory effects in the setting of acute liver inflammation." (PMID 36389734, 2022).
lung fibrosis (12 papers, 2015 to 2024). "In a study of cutaneous systemic sclerosis patients, CCL4 was augmented along with elevation of myeloid dendritic cells in patients with lung fibrosis." (PMID 33598430, 2020). "Although a link between CCL4 and radiation-induced toxicity has been previously unappreciated, CCL4 (also known as MIP-1 beta) has been reported to be elevated in the bronchiolar lavage fluid of patients with lung fibrosis as compared to healthy controls." (PMID 33598430, 2020). "Previous studies showed elevated levels of CCL2, CCL3, and CCL4 in patients with mustard gas-induced pulmonary fibrosis." (PMID 30867053, 2019). "In a recent report, it was discovered that the CCR5 ligands CCL3 (macrophage inflammatory protein (MIP)‐1) and CCL4 (MIP‐1) are both considerably raised in BAL fluid of patients with idiopathic pulmonary fibrosis and have an essential impact in animal models of lung fibrosis." (PMID 37647429, 2023). "However, local depletion of CD11c+ myeloid cells increases CCL4 and CCL11 in the lungs, which are critical for leukocyte chemoattraction and lung fibrosis." (PMID 39582275, 2024). "Here, we also demonstrate that CXCL10, CCL4, CXCL8 and IL-6-producing classical, non-classical monocytes and mDC profile identify a subset of patients characterized by the presence of lung fibrosis and decreased lung function." (PMID 29127442, 2018).
oral squamous cell carcinoma (12 papers, 2017 to 2025). "In particular, higher serum CCL4 levels in patients with oral squamous cell carcinoma (OSCC) are associated with a more advanced stage of disease." (PMID 29599774, 2018). "The purpose of this study was to identify gene polymorphisms of CCL4 specific to patients with oral squamous cell carcinoma (OSCC) susceptibility and clinicopathological characteristics." (PMID 28404909, 2017). "CCL4 has also previously been identified in healthy human oral mucosa tissue, and increased expression of CCL4 was noted in oral squamous cell carcinoma tissue of both humans and mice, indicating its possible effects in disrupting oral cavity tissue growth." (PMID 41226636, 2025). "CCL4 is recognised as a chemokine‐attracting T‐cell, including Tregs, but it also promotes angiogenesis via angiopoietin‐2 in oral squamous cell carcinoma." (PMID 39702941, 2024). "CCL3 and CCL4 are considered potential biomarkers of oral squamous cell carcinoma, and they are also related to monocyte aggregation and inflammatory infiltration, but there are few studies on their relationship with oral flora." (PMID 37957648, 2023). "For example, miR-195-3p inhibited cervical cancer cell proliferation by targeting BCDIN3D, and reversed CCL4-enhanced VEGF-C expression in Oral Squamous Cell Carcinoma." (PMID 34980201, 2022). "Interestingly, CCL4 has been found to promote p-MEK, p-ERK1/2, and p-STAT3 activation, leading to increased angiopoietin 2 expression, thereby facilitating angiogenesis in oral squamous cell carcinoma." (PMID 38739303, 2024).
prostate carcinoma (12 papers, 2009 to 2025). A carcinoma that arises from epithelial cells of the prostate gland. "CCL-4 expression reportedly increases on the surface of prostate cancer cells, which causes changes in the integrin pathway and exacerbates the development and metastasis of prostate cancer." (PMID 37593100, 2023). "Recent evidence suggests that increased CCL4 expression enhances the invasion and migration of prostate cancer cells 40 and promotes tumor growth and angiogenesis." (PMID 40092701, 2025). "Several studies on ovarian and prostate cancer show that CCL4 creates instability in the tumor microenvironment and, probably, facilitates carcinogenesis by stimulating angiogenesis and tumor progression." (PMID 40149697, 2025). "Previous studies have shown that an increase in the expression of ccl4 contributes to migration and tumor invasion by modulating integrin pathway activation in prostate cancer." (PMID 35463731, 2022). "Increased CCL4 expression in prostate cancer cell promoted tumor invasion and migration by modulating integrin pathway activation." (PMID 28404909, 2017). "It was reported that highly expression of CCL4 was significantly positive correlation with lymph node metastasis in diffuse type gastric cancer and metastatic potential in prostate cancer." (PMID 28404909, 2017). "Both CX3CL1 and CCL4 are chemokines involved in attracting immune effector cells, such as natural killer cells and T lymphocytes, although they appear to exert opposing influences on prostate cancer behavior." (PMID 41065832, 2025). "CCL4 is involved in prostate carcinogenesis through macrophage AR signaling, while the CCL21-CCR7 axis in prostate cancer cells is activated by tumor necrotic factor, which is secreted when androgen/AR signaling is inhibited." (PMID 30871130, 2019). "In line with our observed effects of serum from exercise-trained pancreatic and prostate cancer patients, the growth of BC cells was notably inhibited when supplemented directly with recombinant myokines C-X-C motif ligand 1 (CXCL1), Interleukin 10 (IL10), and C-C motif chemokine ligand 4 (CCL4)." (PMID 39518934, 2024).